CD4 (CD4 molecule)
Diseases named in the same sentence as CD4 in open-access papers (continued):
Sharing a sentence is not in itself a finding about the gene and the disease.
Autoimmunity (continued). "In addition, the attack of CD4 + cells on autologous pituitary–gonadal regulatory axis could lead to enhanced ovarian function in the early stages and subsequent development of autoimmune POI." (PMID 38831179, 2024). "Additionally, TAM induced a shift of mouse CD4+ cells from a Th1 phenotype toward a Th2 phenotype, modulating the immune response and dampening anti-tumoral immunity but also inflammation in case of autoimmunity." (PMID 38659456, 2024). "Thus, miR-150 has a critical role in buffering the initial T cell response that could otherwise promote autoimmunity as observed in CD4+ T cells from Myasthenia Gravis patients." (PMID 36817480, 2023). "Activated CD4+ T cells can interact with B lymphocytes to produce autoantibodies that attack neuromuscular junctions, disrupt self-tolerance and induce autoimmunity, whereas T helper type 17 (Th17) cells produce the interleukin (IL)-17 and induce inflammation and autoimmunity." (PMID 37781409, 2023). "Furthermore, during immune homeostasis, there is a balance between the activity of pro- and anti-inflammatory T cells, thereby maintaining immune surveillance while avoiding autoimmunity, whereas the differentiation of naive CD4 T cells can be controlled by several key immune molecules." (PMID 36341399, 2022). "Combining chromatin and transcriptome analyses with functional studies, we have searched for the genes sensitive to survivin inhibition and present a previously unknown survivin-dependent mechanism that coordinates metabolic adaptations during the activation of CD4+ T cells in autoimmunity." (PMID 36425763, 2022). "Therefore, C. jejuni induced autoimmunity is IL-4 and CD4 T cell-dependent." (PMID 35442154, 2022). "Regulatory CD4+ T cells (Treg) expressing the linage specific transcription factor forkhead box P3 (FoxP3) are indispensable for the maintenance of peripheral self-tolerance and thus for the prevention and control of inflammation and autoimmunity throughout entire life." (PMID 36389689, 2022). "The circulating CD4+CXCR5+FOXP3+ Tfrs with enhanced suppressive function could alleviate autoimmunity in RA patients by reducing IgG and IgM levels, and the proportion of Tfrs was negatively correlated with the disease severity, which provided a novel insight into RA pathogenesis." (PMID 35474948, 2022). "Therefore, macroautophagic self-antigen processing for MHC class II presentation in lymphatic endothelial cells and the macroautophagy machinery in dendritic cells might sustain regulatory CD4+ T cell function in tissues to prevent autoimmunity." (PMID 35309359, 2022). "Subtle differences in the phenotype of the CD4+ T cells, specifically TEM cells, highlight IL-6-regulated pathways of interest, including the apoptotic pathway that may contribute to observed association of this IL6R SNP for development of autoimmunity." (PMID 35911690, 2022). "With the consumption of CD4+ T cells, the decrease of regulatory T cell function, the decrease of progressive lymphocytes, and the aging immune system lead to the proliferation of steady-state lymphocytes, which has the characteristics of autoimmunity and excessive inflammation." (PMID 35387441, 2022). "It is noteworthy that PSGL-1 appears to regulate both CD4+ and CD8+ T cells comparably with respect to survival and function, and we do not find that Selplg-/- mice develop spontaneous inflammatory responses or signs of autoimmunity as do mice that are deficient in PD-1 and CTLA-4." (PMID 34326837, 2021). "Alternatively, the lack of autoimmunity in Cd25Y129H mice could also reflect a loss of IL-2R function in autoreactive CD4+ and CD8+ T cells." (PMID 33408345, 2021). "The loss of ctla-4 in CD4+ T cells and Foxp3+ regulatory T cells was found to expand not only the effector T cells but also of CD4+Foxp3+ regulatory T cells, leading to new and unexpected insights into the function of CTLA-4 in peripheral tolerance, development of autoimmunity, and tumor immunity." (PMID 34912335, 2021).
Autoimmunity (continued). "Notably, dysregulation in CD4+ T cell immune responses may result in failure to protect the host from an infection or can lead to autoimmunity." (PMID 34220854, 2021). "Bystander activation of CD4 T cells may play important roles in infection, autoimmunity and cancer." (PMID 34569899, 2021). "Besides the induction of PD-L1 expression in tumor cells, IL-27 may have additional immune-suppressive activities through the induction of IL-10-producing or PD-L1-expressing regulatory-type CD4+ T cells, such as described in autoimmunity and GVHD models." (PMID 34439164, 2021). "Across infection, autoimmunity, and aging, one common theme is the presence of chronic antigen burden, which may explain the generation or persistence of cytotoxic CD4+ T cells in each of these situations, although the contribution of disease-specific contexts must still be carefully considered." (PMID 34910940, 2021). "CD4+ FOXP3+ CD25+ Tregs are the subpopulation of CD4+ T-cells specialised in the suppression of immunopathogenic responses from the host immune system against self or foreign antigens, and contribute to inhibition of autoimmunity and resolution of productive effector T-cell responses." (PMID 32937961, 2020). "Therefore, pDCs and monocytes could play a role during the initiation of T1D, both by initiating inflammation through IFN-α and augmenting autoimmunity by activating CD4 + T cells." (PMID 32483133, 2020). "The combined cellular and humeral autoimmunity theory entertains the thought that along with autoreactive T lymphocytes’ escape into the periphery, a linking step, leading to activation of humeral immunity through the interaction of CD4 T lymphocytes and B lymphocytes, is required." (PMID 32277368, 2020). "Regarding the roles of proinflammatory cytokines in autoimmunity, it is essential to consider the balance between different T cell subsets, mainly divided into two hypotypes according to their function and phenotypes: CD4+ helper T (Th) cell and CD8+ cytotoxic T (Tc) cell." (PMID 32328136, 2020). "It indirectly influences the production of virtually all T cell-derived cytokines and promotes the proliferation of both CD4(+) and CD8(+) T cells, and it may block autoimmunity by affecting the development of CD4(+), CD25(+) T-regulated cells during thymus development." (PMID 33233727, 2020). "In addition, telomerase insufficiency and shorter TL due to defective TERT and TERC expression were observed in naïve CD4 T cells from patients with rheumatoid arthritis, through which premature senescence of T cell subsets occurred and subsequent autoimmunity was triggered." (PMID 32366311, 2020). "In the context of autoimmunity, although some priming in the target tissue may occur, most studies suggest that self-specific CD4 T cells are first primed in the dLN, suggesting that a similar phenomenon might be happening in the generation of an anti-tumor immune response." (PMID 31143179, 2019). "These are broadly separated into two subsets: effector CD4+ T cells, which are key in host defence against pathogens (Th1, Th2, Th9, Th17), and a regulatory CD4+ subset, which dampen the immune response to aid prevention of autoimmunity (Tr1, Th3, nTreg, iTreg)." (PMID 31336952, 2019). "In view of the fact that the CD4+CD28− T cell population exhibits high proinflammatory activity and pathogenic potential to induce tissue destruction, these cells may participate in the pathogenesis of autoimmunity." (PMID 29370129, 2018). "Taken together, a natural gap in negative selection of α-MyHC-specific CD4+ T cells can explain susceptibility to heart-specific autoimmunity in the context of tissue damage, self-antigen release, or exposure to pathogen-derived molecules mimicking cardiac proteins." (PMID 30035131, 2018).
Autoimmunity (continued). "This study introduces the first evidence that PD-1 plays a critical role in helminth infection-attenuated CIA in a mouse model by regulating the CD4+ T cell function, which may provide the new insights into the mechanisms of helminth-induced immunomodulation of host autoimmunity." (PMID 30093899, 2018). "Along these lines, normalization of CD4+ T cell metabolism by mitochondrial metabolism inhibitor metformin and the glucose metabolism inhibitor 2-Deoxy-d-glucose reduced IFNγ production from CD4+ T cells in vitro and suppressed autoimmunity and nephritis in B6.Sle1.Sle2.Sle3 mice and NZB/W F1 mice." (PMID 29868033, 2018). "Recently, CD4+ T cell sub-populations, Treg and Th17 cells, have drawn increased attention, and emerging evidence shows that the novel cytokine IL-35 and regulation of the ratio of these cell types play an important role in the development of autoimmunity and immune tolerance." (PMID 29236782, 2017). "Thus, thymic B cells may affect autoimmunity partly by regulating the thymic CD4 or CD8 lineage ‘decision’ to control the ratio of peripheral CD8+ to CD4+ T cells and IL-17-producing T cells." (PMID 29163765, 2017). "Notably, the inhibitory functions of CTLA-4 on CD4+ T cells appear to be more important for the prevention of autoimmunity as CTLA-4-deficient CD8+ T cells are incapable of inducing autoimmune pathology in the absence of CD4+ T cells." (PMID 28443090, 2017). "Since naïve CD4 T cells may differentiate into Th1, Th2, Th17, and regulatory T (Treg) cells during T cell receptor (TCR) activation in a particular cytokine milieu involved in autoimmunity, we characterized each subtype of CD4+ T cells in the EAE-induced spinal cord." (PMID 27450563, 2016). "In the context of autoimmunity, our data demonstrate that several major determinants of T cell encephalitogenicity, including T-bet, IL-12, and IL-6, skew IL-7Rα/PD-1 balance towards IL-7Rα, favoring an encephalitogenic phenotype of myelin-specific CD4 T cells with enhanced effector function." (PMID 27912762, 2016). "In addition, CD4/8DN T cells may play a variety of roles in the immune system, such as immune response, autoimmunity, immune tolerance in transplantation, and antitumor activity." (PMID 27340921, 2016). "Because IL-2 regulates the differentiation of the TH1, TH2, and TH17 CD4+ T helper cell subsets, we hypothesized that part of the mechanism by which IL-2 counteracts autoimmunity could be via an alteration in the balance of these cell types and the cytokines that they produce." (PMID 27095999, 2015). "HTLV-1-induced changes in the activity of regulatory CD4 T-cell molecules affect the homeostasis of cytokines, including IFN- γ, TNF-α, TGF-β and IL-10, and disrupt the balance in inflammatory and anti-inflammatory responses, leading to the loss of tolerance and the development of autoimmunity." (PMID 26712781, 2015). "Our data suggest that peripheral CD4+ T cell tolerance can be maintained through the combined effects of the two mechanisms and indicate that approaches to modulate Aire expression in DCs could be a potential method to control autoimmunity." (PMID 26729097, 2015). "This combination of abnormalities may make them uniquely suited to take up and process auto-Ags and present the relevant peptide to autoreactive CD4+ T cells, thus contributing to the break in T-cell tolerance and the upregulation of autoimmunity in patients with SLE." (PMID 26209442, 2015). "Due to the fact that late-differentiated memory CD4+ T cells very often showed crossreactivity 27, alloreactivity 28 and autoreactivity 29–31, the lack of IL-16 and Treg lymphocytes may lead to enhanced inflammation and eventually promotion of autoimmunity." (PMID 26029366, 2015). "No causative role of CD4+ T cell aging has been shown in autoimmunity." (PMID 24586733, 2014).
Autoimmunity (continued). "Therefore, increased diversion to the Treg lineage/Treg suppression and CD4 T cell anergy might cooperate to suppress the emergence of autoimmunity in these mice." (PMID 25182415, 2014). "Because CD4+ regulation is essential to prevent autoimmunity during immunoglobulin class-switching, our findings may partially explain detection of auto-antibodies in advanced COPD, especially given the observation that CD40L appears reduced in Group A subjects (p = 0.055)." (PMID 24805101, 2014). "Moreover, peptide-bound gp120 avoids complications of potential CD4 autoimmunity." (PMID 24304511, 2013). "Although NIK deficiency only in the thymic stroma suffices to produce CD4+ T cell-mediated autoimmunity and altered Treg generation, it is not known whether NIK also plays a cell-intrinsic role in thymic Treg generation or peripheral Treg maintenance." (PMID 24073289, 2013). "This may prevent apoptosis of CD4+ T cells, which is important in the development of autoimmunity." (PMID 24286013, 2013). "The vessel-associated movement of CD4+ T cells in contrast to CD8+ T cells seems also to be important for regulatory T cell subtypes independent of antigen specificity and underlines the importance of the perivascular space for immunoregulation and autoimmunity." (PMID 21978405, 2011). "Using TPLSM, we previously showed that activated CD4+ effector T cells are attracted to the CNS's perivascular space and reveal a CXCR4 dependent and vessel-associated migration pattern, suggesting this compartment is highly relevant for autoimmunity and immunoregulation." (PMID 21978405, 2011). "Thus, autoimmunity to CD4 in HIV-1 infected patients is supported by several mechanisms associated with the generation of cryptic epitopes and to the activation of T cells not previously deleted by central tolerance during the maturation of the T cell repertoire." (PMID 19943950, 2009). "In autoimmunity, TCRαβ+ CD3+ CD4− CD8− T cells were described as a small subset of peripheral T cells, capable of expanding in several autoimmune conditions, such as psoriasis, Sjogren syndrome, systemic lupus erythematosus (SLE)." (PMID 41416941, 2025). "An imbalance between Th17 cells (promote tissue inflammation) and T-reg cells (suppress autoimmunity in IBD), which are differentfrom CD4+ T-cells, contribute to IBD." (PMID 41009629, 2025). "It increases the level of lymphocytes in all compartments (CD4+, CD8+ and B), but we confirmed that these cells are mainly the naïve populations that are particularly useful in fighting against autoimmunity." (PMID 39835539, 2025). "We conclude that CD4+ and CD8+ Treg cells have overlapping yet distinct roles in regulating cellular and humoral responses and preventing autoimmunity." (PMID 39806065, 2025). "As performed before, we used gene module scores of classical TRM CD4 T cells from healthy lung, skin, and jejunum, liver TRM-like CD4 T cells during HBV infection or HCC, and of TPH cells from synovial fluid during autoimmunity." (PMID 39880819, 2025). "CD4+LAP+T cells are highly active and protect against autoimmunity in experimental models of encephalomyelitis, systemic lupus erythematosus, colitis, and diabetes." (PMID 40270513, 2025). "Notably, TCF1‒CXCR6+ effector cells have also been identified across various CD4+ T-cell-mediated immune responses, highlighting the need for further studies to define their molecular regulation and precise role in driving tissue damage in autoimmunity and allograft rejection." (PMID 40634636, 2025). "Our results highlight the differential roles of CD4+ and CD8+ Treg cells in regulating autoimmunity, potentially by targeting different cellular activities and involvement in different stages of autoimmune development." (PMID 39806065, 2025). "While CD4+ TRM are highly protective during reinfections or tumor growth, they are also critical mediators of autoimmunity and allergic disease." (PMID 41256356, 2025).
Autoimmunity (continued). "Instead, this fully activated CD4+ T cell will be converted into a clone of TREG cells (and memory TREG cells), and understandably, their function is to suppress autoimmunity against this particular self-antigen in the peripheral tissues." (PMID 41296449, 2025). "In all these models, it appears that the transient lymphopenic milieu, more than CD4+ CD25+ T cell depletion, promotes autoimmunity." (PMID 38404584, 2024). "We found a positive correlation between GADA titer and the proportion of MAIT (p = 0.026) and CD4 TEM cells (p = 0.086), suggesting a possible role for these cell types in GAD autoimmunity." (PMID 38539228, 2024). "The TBI-IMID showed an increase of Mtb-specific CD153+ CD4+ T cells compared to TBI, supporting the role of autoimmunity in the CD153-expression." (PMID 39872515, 2024). "CD4 + CD25 + FOXP3 + regulatory T cells (Tregs) are essential for maintaining immune tolerance and preventing autoimmunity." (PMID 39372653, 2024). "T-cell infiltrates are a key indicator of a high concentration of CD4+ T cells, particularly regulatory T cells (Tregs) like CD4 + CD25+ Tregs, which are vital for maintaining self-tolerance and preventing autoimmunity." (PMID 39768826, 2024). "Upregulation of IL-21 in infiltrating CD4+ T cells and its expression by clonally expanded T cells suggest a critical role for IL-21 signaling in PNS autoimmunity development." (PMID 39087473, 2024). "The proliferation, activation, and effector function of CD4+ and CD8+ T-cells were negatively modulated by LAG3 expression, which has also been reported to regulate autoimmunity." (PMID 39698464, 2024). "Finally, the majority of studies have mainly focused on addressing the pathogenic role of cDC2 directly activating CD4+ or CD8+ T cell responses in the context of autoimmunity, without considering the potential influence of other innate immune cells such as NK cells." (PMID 37916875, 2023). "After relaying, CD4+ CD25- T cells recognize specific antigens on the prostate tissue of C3.129 nu/nu mice and induce autoimmunity to occur, which attacks the prostate tissue and damage occurs, resulting in prostatitis." (PMID 37228599, 2023). "The pathological features revealed marked inflammatory responses in perivascular regions, including CD4+ T cells, CD8+ T cells, B cells, plasma cells, macrophages, and neutrophils in autoimmune GFAP astrocytopathy." (PMID 37458208, 2023). "Previous studies have shown that CD4+ cells in IPF are highly activated and exhibit exuberant responses when stimulated with autologous IPF lung extracts, suggesting a process of autoimmunity in IPF through recognition of self-antigens." (PMID 37275887, 2023). "Overall, our study clarified a novel mechanism that DNA accumulation in CD4+ T cell potentiates glycolysis and OXPHOS, which also explains the nosogenesis of DNA accumulation leading to autoimmunity diseases." (PMID 39872301, 2023). "Although less well-studied than their CD4+ counterparts, CD8+ T cells are receiving increasing attention as agents involved in the development of autoimmunity, and particularly SLE, due to both their inflammatory and protective functions." (PMID 38203623, 2023). "Hence, HTLV-1-induced changes in regulatory CD4 T-cell molecules activity affects the homeostasis of cytokines such as IFN-γ, TNF-α, TGF-β, and IL-10, which disrupts the balance in anti-inflammatory and inflammatory responses, resulting in the loss of tolerance and the development of autoimmunity." (PMID 37293205, 2023). "Further research with larger series and more specific approaches are needed to fully understand the role of CD4 and CD8 Tregs in the pathogenesis and clinical manifestations of CVID and its relationship with autoimmunity." (PMID 38259469, 2023).